LTBP2 (latent transforming growth factor beta binding protein 2)
Diseases named in the same sentence as LTBP2 in open-access papers (continued):
Sharing a sentence is not in itself a finding about the gene and the disease.
aortic stenosis (2 papers, 2020 to 2024). Aortic valve stenosis is a aortic valve disease caused by the incomplete opening of the aortic valve. "In humans, null mutations in LTBP2 cause WMS3, a recessive syndrome characterized by short stature, brachydactyly, joint stiffness, and pulmonary and aortic stenosis." (PMID 39768188, 2024).
breast carcinoma (2 papers, 2020 to 2022). "In breast cancer lung metastases, stromal POSTN is crucial for cancer stem cell maintenance by increasing Wnt signaling 36, and LTBP2+/POSTN+ CP-CAFs constitute the majority of ECM-CAFs." (PMID 36438498, 2022).
Cirrhosis (2 papers, 2022 to 2024). A chronic disorder of the liver in which liver tissue becomes scarred and is partially replaced by regenerative nodules and fibrotic tissue resulting in loss of liver function. "We found them to be upregulated in cirrhosis represented by the upregulation of PGDFRB, TGFB1 (TGF‐β1), TGFB1I1 (TGF‐β1 induced transcript 1 protein), TGFBI (TGF‐β induced protein ig‐h3), LTBP1, LTBP2, LTBP4, and ENG (transmembrane accessory receptor for TGF‐beta signaling)." (PMID 35579278, 2022).
COVID-19 (2 papers, 2021 to 2022). A disease caused by infection with severe acute respiratory syndrome coronavirus 2. "As LTBP2 was a secreted protein, we measured serum LTBP2 concentrations in patients with PF secondary to COVID-19." (PMID 35002722, 2021). "Moreover, serum LTBP2 was also elevated in patients with COVID-19-related PF." (PMID 35002722, 2021). "In this study, we investigated LTBP2 expression in three PF with different pathological origins: IPF, RA-ILD and COVID-19-related PF." (PMID 35002722, 2021). "In the present study, we identified that LTBP2 is upregulated in different types of patients with PF, including IPF, RA-ILD, and COVID-19-related PF, and in mice following BLM-induced PF." (PMID 35002722, 2021). "Our data showed that LTBP2 expression was up-regulated in patients with IPF, RA-ILD and COVID-19-related PF." (PMID 35002722, 2021). "However, our study has limitations in BLM-induced PF murine model and it would be necessary to use different animal models to further evaluate the exact role of LTBP2 in RA-ILD and COVID-19-related PF in future studies." (PMID 35002722, 2021).
dementia (2 papers, 2023 to 2025). Loss of intellectual abilities interfering with an individual's social and occupational functions. "Further, we identified ACTA2, LTBP2, and NCS1 as potential contributors to dementia risk." (PMID 38016990, 2023).
dilated cardiomyopathy (2 papers, 2022 to 2024). Cardiomyopathy which is characterized by dilation and contractile dysfunction of the left and right ventricles. "Studies looking at dilated cardiomyopathy and right ventricular failure have also implicated LTBP2 function in fibrosis regulation which may indicate a role in the pathogenesis of trabecular meshwork dysfunction." (PMID 38682030, 2024). "Ltbp2 is also upregulated in the LV of a rat model of dilated cardiomyopathy and congestive heart failure." (PMID 36388115, 2022). "Importantly, knockdown of Ltbp2 in this model decreases reactive oxygen species and malondialdehyde, and this reduction in oxidative stress is associated with a decrease in LV fibrosis and adverse remodelling, indicating a role for Ltbp2 in the pathogenesis of dilated cardiomyopathy." (PMID 36388115, 2022).
endometriosis (2 papers, 2022 to 2024). The growth of functional endometrial tissue in anatomic sites outside the uterine body. "Recent investigations have suggested that overexpression of LTBP2 facilitated inflammation in endometriosis." (PMID 36671424, 2022).
fibrosis (2 papers, 2025). the formation of excess fibrous connective tissue in an organ or tissue in a reparative or reactive process. "Intriguingly, we found that treatment of cultured fibroblasts from bleomycin-treated mice with anti-LTBP2 antibody impaired migration in a similar manner to LTBP2 gene deletion, suggesting that LTBP2 targeting by antibody may have salutary effects in fibrosis." (PMID 40654695, 2025).
infantile hemangiomas (2 papers, 2013 to 2019). "In addition, Ltbp2 has also been shown to be dysregulated in infantile hemangiomas, linking it to other vascular pathologies." (PMID 31426861, 2019).
keloid (2 papers, 2015 to 2017). An irregularly shaped, elevated mark on the skin caused by deposits of excessive amounts of collagen during wound healing. "We have recently shown that LTBP-2 is highly expressed in fibrotic skin conditions, keloids, and hypertrophic scars." (PMID 28991210, 2017). "Confocal microscopy showed strong co-localisation of LTBP-2 and FGF-2 in fibrotic keloid tissue suggesting that the two proteins may interact in vivo." (PMID 26263555, 2015).
liver cancer (2 papers, 2019 to 2024). An epithelial or non-epithelial malignant neoplasm that arises from the liver. "For example, the protein with the highest importance that also had a strong correlation (0.82, Pearson) with the ELF score, LTBP2, is overexpressed in the fibrotic livers of PSC patients and was reported as a prognostic biomarker for liver cancer." (PMID 38892228, 2024).
meningioma (2 papers, 2007 to 2022). A generally slow growing tumor attached to the dura mater. "We noticed that genes such as TGFBI, SNAI1, MMP2, TGFB1, TGFB2, IGFBP7, and LTBP2 were upregulated by the treatment of M2-MDEs in meningioma cells and may contribute to tumor invasion and proliferation behavior." (PMID 35637794, 2022). "In addition, we found induction of IGFBP3, CENPF, CKS2 and reduction of LTBP2, PTPRF in high-grade meningiomas as previously reported." (PMID 17937814, 2007).
Myocardial fibrosis (2 papers, 2021 to 2024). "Knockdown of LTBP2 using siRNA resulted in reduced myocardial fibrosis, inflammation and oxidative stress through a reduction in NF-kB signaling." (PMID 38727290, 2024). "A previous study showed that LTBP2 knockdown by siRNA reduced the degree of myocardial fibrosis by suppressing activation of the NF-κB signaling pathway." (PMID 35002722, 2021). "This is in line with several studies that LTBP2 knockdown decreased collagen expression in myocardial fibrosis and ECM gene expression in trabecular meshwork cells." (PMID 35002722, 2021). "Previous data have shown that LTBP2 knockdown inactivated the NF-κB signaling pathway, subsequently decelerating the progression of myocardial fibrosis." (PMID 35002722, 2021).
myopia (2 papers, 2018 to 2025). "The phenotypic subset associated with myopia (n = 130) was found to represent a set of 119 unique genes since 7 genes (COL2A1, COL11A1, FBN1, LTBP2, POMT1, POMT2, POMGNT1) had two or more associated phenotypes, leading to 11 duplicates." (PMID 29346494, 2018).
prostate carcinoma (2 papers, 2024). A carcinoma that arises from epithelial cells of the prostate gland. "In prostate carcinoma, LTBP2 protein increases in parallel with CD4+ T-cell infiltration and immune checkpoint blockade." (PMID 39201614, 2024).
pulmonary hypertension (2 papers, 2022 to 2025). Increased pressure within the pulmonary circulation due to lung or heart disorder. "While the role of Ltbp2 in PAH associated RVF has not been studied, a recent study confirmed that a 2bp insert into this gene resulted in an infant with clinical features that included pulmonary hypertension with right ventricular impairment." (PMID 36388115, 2022).
aneurysm (1 paper, 2017). Bulging or ballooning in an area of an artery secondary to arterial wall weakening. "Because fibrillin-1 is the main component of microfibrils, we reasoned that microfibril defects in Ltbp2/4S DKO mice could cause aneurysms, which turned out not to be the case." (PMID 28252045, 2017).
asthma (1 paper, 2025). "We additionally observed increased LTBP2 expression in the airway walls of severe asthma, and further defined the cell types responsible for LTBP2 production at homeostasis and in disease using publicly available scRNASeq data." (PMID 40654695, 2025). "We show that LTBP2 is expressed in IPF lungs and remodeled airways of COPD, and asthma, that its deletion is associated with decreased fibrosis and reduced TGFβ signaling, and that its expression is required for effective airway repair after injury." (PMID 40654695, 2025). "In representative samples of at least three different lungs, LTBP2 protein expression was minimal in control lungs but increased in each disease, marking parenchymal fibrosis in IPF and remodeled airways in COPD and asthma." (PMID 40654695, 2025). "To confirm that LTBP2 expression is increased in remodeled regions of diseased lung, we used immunofluorescence microscopy in control donor lungs, end-stage explants of IPF and COPD lungs, and donor lungs with severe asthma." (PMID 40654695, 2025).
atherosclerosis (1 paper, 2021). A disease characterized by the build-up of fatty material and calcium deposition in the arterial wall resulting in partial or complete occlusion of the arterial lumen. "Whether the rest of them, including Dkk2, Ltbp2, Lamb1, Cdca7l, Dclk1, and Slc45a4, are associated with atherosclerosis and d-flow has not been reported." (PMID 34282126, 2021).
cervical (1 paper, 2016).
Chronic colitis (1 paper, 2019). A chronic inflammatory disease of the large intestine (colon, cecum and rectum). "We determined LTBP2 protein expression in 483 archived tissue blocks including 204 cancer tissues, 190 matched normal surgical margins, 23 chronic colitis tissues, 44 low-grade intraepithelial neoplasia tissues, and 22 high-grade intraepithelial neoplasia tissues." (PMID 30956730, 2019).
chronic obstructive pulmonary disease (1 paper, 2022). A chronic and progressive lung disorder characterized by the loss of elasticity of the bronchial tree and the air sacs, destruction of the air sacs wall, thickening of the bronchial wall, and mucous accumulation in the bronchial tree. "Plasma Ltbp2 levels predict all-cause mortality, particularly pulmonary death, in patients with acute dyspnoea (including patients with chronic obstructive pulmonary disease and pneumonia acute pulmonary embolism)." (PMID 36388115, 2022).
Coffin-Siris syndrome (1 paper, 2021). Coffin-Siris syndrome (CSS) is a rare congenital multi-systemic genetic disorder characterized by aplasia or hypoplasia of the distal phalanx or nail of the fifth digit, developmental delay, intellectual disability, coarse facial features, and other variable clinical manifestations. "The group of non-acquired systemic diseases included a Weill–Marchesani case with LTBP2 mutation, a patient with Coffin–Siris syndrome with SOX11 mutation, and one case with Sturge–Weber syndrome." (PMID 35011756, 2021).
complication (1 paper, 2017). Any disease or disorder that occurs during the course of, or because of, another disease, treatment, or procedure. "The greater angiogenic potential of T2DM–BMMSCs secretome may reflect the interactive actions of multiple bioactive mediators (including IGF‐1, LTBP1 and LTBP2) which may alter the functions of endothelial cells, key players in diabetic vascular complications." (PMID 27641937, 2017).
diabetes (1 paper, 2024). "Together, these results reveal dapagliflozin can delay natural kidney senescence in non-diabetes environment; the mechanism may be through regulating the role of LTBP2." (PMID 38454800, 2024).
emphysema (1 paper, 2017). "Further study is necessary to examine the role of TGF-β signaling in the pathogenesis of the emphysema present in Ltbp2/4S DKO mice." (PMID 28252045, 2017). "Ltbp2/4S double knockout (DKO) mice showed increased lethality due to emphysema, which was much more severe than that found in Ltbp4S null mice." (PMID 28252045, 2017). "Macroscopic examination confirmed obvious emphysema in Ltbp4S mice, and notably, Ltbp2/4S DKO mice showed a more severe form of emphysema than that found in Ltbp4S null mice." (PMID 28252045, 2017). "A more severe form of emphysema than that in Ltbp4S null mice was the only critical phenotype we observed that could affect the life span of Ltbp2/4S DKO mice." (PMID 28252045, 2017). "Elastic fibers in the lungs of Ltbp2/4S DKO mice were markedly fragmented, which could account for the severe emphysema observed." (PMID 28252045, 2017). "While Ltbp4S null mice show emphysematous lungs and Ltbp2 null mice have no phenotype in organs other than the eyes, Ltbp2/4S DKO mice exhibit a much more severe form of emphysema than that found in Ltbp4S null mice, which was associated with increased mortality." (PMID 28252045, 2017).
Hypertension (1 paper, 2016). The presence of chronic increased pressure in the systemic arterial system. "In the current study, only 3 genes associated with hypertension (Ephx2, Cst3 and Ltbp2) appeared on the list of the top 40 DEGs that make the largest contribution to inter-strain differences." (PMID 26822062, 2016). "According to RGD annotations, there were several genes related to CNS diseases (Abcg2, Ephx2, RGD1563482, Tgfb2, Mal, and Cst3), and 3 genes associated with hypertension (Ephx2, Cst3, and Ltbp2) are found on this list." (PMID 26822062, 2016). "In the current study, we defined 3 genes associated with hypertension (Ephx2, Cst3 and Ltbp2) that might be of interest for further studies as potential therapeutic targets for stress-sensitive hypertension therapies." (PMID 26822062, 2016). "Of the top 40 DEGs making the greatest contribution to the interstrain differences, there were 3 genes (Ephx2, Cst3 and Ltbp2) associated with hypertension that were considered to be suitable for further studies as potential targets for the stress-sensitive hypertension therapy." (PMID 26822062, 2016).
intrahepatic cholangiocarcinoma (1 paper, 2022). A carcinoma that arises from the intrahepatic bile duct epithelium in any site of the intrahepatic biliary tree. "Moreover, we showed that in intrahepatic cholangiocarcinoma, in which ECM-remodeling CAF proportion is similar to that of CRC-LM, several genes expressed by ECM-remodeling CAFs, such as LTBP2, were associated with survival." (PMID 36438498, 2022).
lipodystrophy (1 paper, 2021). A congenital or acquired disorder characterized by abnormal loss or redistribution of the adipose tissue in the body. "We next analyzed how the downregulation of Ltbp2, Nebl, and Wisp2 might affect processes involved in lipodystrophy, such as adipocyte differentiation." (PMID 34383714, 2021).
Optic neuropathy (1 paper, 2024). "In addition to these patients with possible inherited optic neuropathies, six other patients (20.0% of patients with an alteration of the GCC) carried suspected unique pathogenic variants in six recessive genes (DPYD, AGXT, CYP1B1, ACO2, LTBP2 and FDXR)." (PMID 38796496, 2024). "The susceptibility variants identified in the other six patients were not firmly responsible on their own for a genetic form of optic neuropathy since they were found in recessives genes (DPYD, ACO2, AGXT, CYP1B1, LTBP2 and FDXR) with a single affected allele." (PMID 38796496, 2024).
oral cancer (1 paper, 2025). "Screening of the data revealed eight TRGs (TGFB3, LTBP2, BMP2, TGFB1, ACVR1, CDK9, SLC20A1, and SMURF2) with non-zero coefficients, indicating their association with the prognosis of oral cancer patients." (PMID 38698292, 2025).
polydactyly (1 paper, 2020). A disease characterized by the presence of polydactyly, including syndromic and non-syndromic forms. "The present study demonstrates that in complex CHD associated with polydactyly, the mutations of LTBP2 and TCTN3 may be potential pathological cause since these mutations are associated with changes of cellular functions that may affect the development of the heart." (PMID 33098376, 2020).
Primary glaucoma (1 paper, 2020). "Interestingly, two infants from this cohort who were initially diagnosed with primary glaucoma were found to have a secondary mechanism associated with either LTBP2 or FOXC15 gene defects." (PMID 31848469, 2020).
serous ovarian carcinoma (1 paper, 2016). "High LTBP2 protein expression predicts poor survival in serous ovarian carcinoma." (PMID 27281608, 2016).
tauopathy (1 paper, 2025). Neurodegenerative disorders involving deposition of abnormal tau protein isoforms (tau proteins) in neurons and glial cells in the brain. "APOE ε4 amplifies tau pathology via hub genes: In P301S tauopathy mice, female APOE ε4 boosted expression of Lrp10, Ltbp2, Lamc1, and Rbms2, revealing a potential link to the acceleration of tau-driven neurodegeneration." (PMID 41409615, 2025).